SLX4IP (SLX4 interacting protein)
Synonyms: C20orf94; dJ1099D15.3; bA204H22.1; bA254M13.1
Tractability: PROTAC: UniProt records ubiquitination sites on it; ubiquitination databases record sites on it; its protein half-life has been measured.
Gene: Protein-coding gene on chromosome 20 (10,435,299 to 10,636,829, forward strand). Ensembl gene ENSG00000149346.
Subcellular location (Human Protein Atlas): Cytosol
Gene Ontology:
Molecular function: protein binding
Genetic constraint (gnomAD): Loss-of-function variants: 34 observed, 40.08 expected, observed/expected ratio (o/e) 0.85, 90% interval 0.64 to 1.13. The upper end of that interval is the gene's LOEUF score, 1.13, which puts it in group 4 of 6, group 1 being the genes least tolerant of losing a copy. Missense variants: 423 observed, 480.07 expected, observed/expected ratio (o/e) 0.88, 90% interval 0.81 to 0.95. Synonymous variants: 166 observed, 172.56 expected, observed/expected ratio (o/e) 0.96, 90% interval 0.85 to 1.09.
Homologues: Orthologues: chimpanzee SLX4IP (97% identical), macaque SLX4IP (93% identical), rabbit SLX4IP (79% identical), dog SLX4IP (72% identical), mouse Slx4ip (69% identical), rat Slx4ip (68% identical), tropical clawed frog slx4ip (35% identical), zebrafish slx4ip (22% identical).
Diseases named in the same sentence as SLX4IP in open-access papers:
SLX4IP is named in the same sentence as 15 diseases in open-access papers, as found by Europe PMC text mining. Sharing a sentence is not in itself a finding about the gene and the disease. The quoted sentences say what the papers report.
acute lymphoblastic leukemia (3 papers, 2019 to 2025). Leukemia with an acute onset, characterized by the presence of lymphoblasts in the bone marrow and the peripheral blood. "Although microdeletions in the SLX4IP gene have been associated with acute lymphoblastic leukemia, the molecular functions of SLX4IP in the context of cancer remain poorly understood." (PMID 32071280, 2020). "Several of these functionally uncharacterized proteins are associated with human diseases including ciliary dyskinesia (CLXN), Lui-Jee-Baron syndrome (SPIN4), lymphoblastic leukemia (LNP1, SLX4IP), lethal skeletal dysplasia (TMEM263), and association to autism and fragile X syndrome (DIPK2B)." (PMID 40425816, 2025).
breast carcinoma (3 papers, 2020 to 2021). "Moreover, SLX4IP expression patterns are associated with specific TMMs, which readily influence the metastatic properties of breast cancer cells and their sensitivity to specific telomere-targeting agents." (PMID 32071280, 2020). "Based on these in vitro results, the investigators then examined the expression level of SLX4IP and hTERT in a large cohort of human breast cancer samples." (PMID 34069193, 2021). "In the D2.0R cells, an ALT+ murine mammary cancer cell line, knockout of SLX4IP resulted in upregulated hTERT, decreased APBs and C-circles, and re-expressed ATRX and DAXX." (PMID 34069193, 2021). "This study illuminates SLX4IP as a potential predictive biomarker for breast cancer progression and metastatic relapse." (PMID 32071280, 2020). "An unbiased genetic screen established SLX4IP as an essential driver of telomere maintenance mechanism identity, metastatic progression, and therapeutic response of breast cancers." (PMID 32071280, 2020). "This study elucidates the utility of SLX4IP as a potential predictive marker of breast cancer metastasis and patient survival and reveals its close connection with telomere homeostatic pathways." (PMID 32071280, 2020). "Interestingly, however, human breast cancer cells seem to be capable of modulating the expression of SLX4IP to switch TMMs to become chemoresistant." (PMID 34069193, 2021). "An interesting report by Robinson and colleagues found that poor prognosis of HER2+ breast cancers may be associated with increased expression of the SLX4 interacting protein, or SLX4IP." (PMID 34069193, 2021). "We next determined whether our murine-based SLX4IP findings could be generalized to human breast cancer models, and more importantly, whether TMMs can also be targeted therapeutically in these systems." (PMID 32071280, 2020). "Taken together, these findings indicate that SLX4IP and TMM identity are strongly associated with disease progression and therapeutic response to ATR inhibitors and 5-FdU; they also suggest that elucidating breast cancer TMM status may provide new insights to inform treatment selection." (PMID 32071280, 2020). "We next assessed the connection between the inverse expression patterns of SLX4IP and TERT and breast cancer patient outcomes, including progression to metastasis." (PMID 32071280, 2020). "The inverse relationship between SLX4IP and TERT was conserved in both TNBC and HER2+ breast cancers, and these aberrations manifested specifically during metastasis to the CNS." (PMID 32071280, 2020). "To address this important question, we used a diverse array of primary breast cell and patient-derived tissue sources to evaluate the relationship between SLX4IP and TERT in human breast cancers." (PMID 32071280, 2020). "Collectively, these findings support a role for SLX4IP in mediating ALT and reinforce the notion of deploying combinatorial approaches to target TMMs in breast cancers." (PMID 32071280, 2020). "Taken together, these results reveal that SLX4IP and TERT are intricately related to one another in distinct human breast cancer subtypes, and this relationship presages metastatic progression and patient survival." (PMID 32071280, 2020). "SLX4IP expression correlates with TMM identity, which also carries prognostic value and informs treatment selection, thereby revealing new inroads into combating metastatic breast cancers." (PMID 32071280, 2020).
leukemia (2 papers, 2019 to 2023). A malignant (clonal) hematologic disorder, involving hematopoietic stem cells and characterized by the presence of primitive or atypical myeloid or lymphoid cells in the bone marrow and the blood. "Interestingly, leukemias with deletions of SLX4IP harbored significantly more RAG-mediated SVs." (PMID 37337105, 2023).
osteosarcoma (2 papers, 2019 to 2021). A usually aggressive malignant bone-forming mesenchymal neoplasm, predominantly affecting adolescents and young adults. "SLX4IP expression is downregulated in aneuploid acute myeloid leukemia cells and a subset of osteosarcoma cells that use the ALT pathway." (PMID 34804132, 2021). "Its importance for the ALT process is underscored by the finding that SLX4IP is inactivated in a subset of ALT-positive osteosarcomas." (PMID 31447390, 2019). "The clinical importance of SLX4IP in the ALT process is highlighted by its inactivation in a subset of ALT-positive osteosarcomas." (PMID 31447390, 2019). "In light of our findings linking SLX4IP to ALT telomere maintenance, we asked whether SLX4IP is inactivated in osteosarcoma tumors, which frequently use the ALT pathway." (PMID 31447390, 2019). "Finally, we show that SLX4IP is inactivated in a subset of ALT-positive osteosarcomas." (PMID 31447390, 2019). "Telomere maintenance in osteosarcomas frequently occurs via the ALT pathway, and we show here that SLX4IP is inactivated in a subset of these tumors." (PMID 31447390, 2019). "To confirm this result, we analyzed the seven osteosarcoma tumor samples for ATRX, DAXX, SMARCAL1, H3.3, and SLX4IP protein expression by immunoblotting." (PMID 31447390, 2019).
breast tumors (1 paper, 2020). "Pairwise analysis of primary breast tumors with matched central nervous system (CNS) metastases uncovered striking patterns of SLX4IP and TERT expression." (PMID 32071280, 2020).
mastitis (1 paper, 2018). Inflammation of breast tissue during lactation or postpartum due to an obstructed duct or infection. "The SNP rs109785134 on BTA13, a missense variant and in significant association with susceptibility to mastitis in parity 3, is located within the protein coding gene SLX4IP (SLX4 interacting protein)." (PMID 29755506, 2018).
cancer (3 papers, 2020 to 2026). A tumor composed of atypical neoplastic, often pleomorphic cells that invade other tissues. "Together, our results define SLX4IP as a critical genome-wide regulator of replication fork integrity and reveal SLX4IP as a potential vulnerability in ALT-positive cancers." (PMID 42098304, 2026). "Collectively, these findings suggest that SLX4IP expression and its association with ALT phenotypes influence cancer cell susceptibility to the anticancer activities of ATR and BLM inhibitors." (PMID 32071280, 2020). "Although the regulators underpinning ALT induction and maintenance are poorly understood, recent evidence suggests that SLX4IP and RAD51AP1 are two essential regulators of ALT telomere maintenance in ALT cancer cells." (PMID 35159266, 2022).
tumor (2 papers, 2019 to 2020). "Consistent with the analysis in our tumor samples, SLX4IP deficiencies in our cell lines are mutually exclusive with ATRX, DAXX, SMARCAL1, and H3.3, raising the possibility that SLX4IP may represent another gene deficiency associated with ALT activity." (PMID 31447390, 2019).
SLX4IP also shares sentences with these, for which no sentence is quoted: autism (1 paper); ciliary dyskinesia (1); fragile X syndrome (1); Lethal skeletal dysplasia (1); Lui-Jee-Baron syndrome (1); Merkel cell carcinoma (1); non-melanoma skin carcinoma (1).